HNRNPC (heterogeneous nuclear ribonucleoprotein C)
Diseases named in the same sentence as HNRNPC in open-access papers (continued):
Sharing a sentence is not in itself a finding about the gene and the disease.
cancer (continued). "Heterogeneous nuclear ribonucleoproteins C and M (hnRNPC, hnRNPM) are RNA-binding proteins belonging to the hnRNP family and have important roles in cancer related to their functions in processing and splicing of RNAs." (PMID 39221819, 2024). "Overexpression of HNRNPC was found in the central regulators of colon rectum cancer cells and cancer progression-related genes." (PMID 37592311, 2023). "hnRNPCs including hnRNPA2/B1, HNRNPC, HNRNPE and HNRNPH are found to be prevalently and significantly up‐regulated expression in a variety of tumors associated with cancer cells metastasis." (PMID 36260366, 2023). "According to their levels of HNRNPC expression, cancer patients were distinguished into high- and low expression groups." (PMID 35344508, 2022). "According to the findings of Fischl, hnRNPC modulates cancer-specific alternative polyadenylation and cleavage." (PMID 35937991, 2022). "To further validate the expression of HNRNPC RNA levels in pan-cancer, we checked the results of GTEx database again." (PMID 35344508, 2022). "IIPA found that SFPQ interacts with many important proteins, such as YY1, RTN4, RICTOR, HDACs, BMI1, and HNRNPC, which are important in the development of cancer." (PMID 35707369, 2022). "Based on the Cancer Genome Atlas and Gene Expression Omnibus datasets, we investigated the possible oncogenic effects of HNRNPC in thirty-three cancers." (PMID 35344508, 2022). "HNRNPC expression was detected in the majority of cancers, and its expression level was shown to be significantly linked with cancer patient prognosis." (PMID 35344508, 2022). "An increasing number of studies have confirmed that m6A writers (METTL3, METTL14, KIAA1429, WTAP), erasers (FTO and ALKBH5) and readers (YTHDC1, YTHDC2, YTHDF1, YTHDF2 and HNRNPC) have distinct functions within different types of cancer cells." (PMID 35042525, 2022). "Additional research revealed that HNRNPC was involved in the processing of cancer-related genes, including BRCA1/2, uPAR, MALAT, PDCD4, and cMyc." (PMID 35344508, 2022). "METTL3, TYTHDF1, YTHFDF2 and HNRNPC were highly expressed in cancer tissues and low in normal control tissues." (PMID 34521394, 2021). "HNRNPC is considered as the promoter of tumorigenesis, and overexpression of HNRNPC can be found in the main regulators of various cancer progression-related genes, which is closely connected to the poor clinical prognosis of cancer." (PMID 34957092, 2021). "Consistent with published articles, HNRNPC can serve as an oncogene, which is overexpressed in various cancers." (PMID 34804925, 2021). "Aberrant up-regulation of hnRNPC has been observed in a variety of cancers or cancer cell lines including breast cancers, glioblastomas, hepatocellular carcinomas, ovarian cancers, and lung cancers." (PMID 33526057, 2021). "In contrast to the relatively known roles of BIRC5, CENPF, and STMMN1 in malignancies, functions of APOC2 and HNRNPC genes in cancer cell are less well defined." (PMID 33828156, 2021). "The 8-mRNAsi based prognostic model in our signatures includes RGS16, LYVE1, hnRNPC, ANP32A, AIMP1, ZNF66, PIK3R3, and MAP2K7, in which several genes have been reported to be linked with stemness features or be involved in cancer progression." (PMID 33329703, 2020). "Among the 13 m6A RNA methylation regulators, only HNRNPC was significantly related to the cancer recurrence." (PMID 32211315, 2020). "HNRNPC, heterogeneous nuclear ribonucleoprotein C1/C2, is a commonly expressed RNA-binding protein with cancer-promoting function." (PMID 32984057, 2020). "We identified hnRNPC as a critical regulator for the establishment of cancer characteristic profiles in a subset of genes including MTHFD1L, which has been strongly linked to cancer progression." (PMID 31147722, 2019).
cancer (continued). "Our approach using distinct cell lines identified characteristic APA profile changes in several cancer relevant genes including SMAD3, PA2G4 and MTHFD1L and linked the latter two to the de-regulation of hnRNPC in metastatic site-derived cells." (PMID 31147722, 2019). "In contrast, hnRNPC is up-regulated and related to clinical outcomes in various cancers." (PMID 40483535, 2025). "Our analysis identified a noteworthy connection between HNRNPC and immune infiltration in 25 distinct cancer types, with positive correlations observed specifically in KIPAN and KIRC, while negative correlations were observed in the remaining 23 types of cancer." (PMID 39735682, 2025). "Given its significant role in RNA editing, HNRNPC could be considered a potential therapeutic target for cancer therapy." (PMID 39735682, 2025). "Just as depletion of hnRNPC or hnRNPM leads to cell death due to sensing of endogenous dsRNAs arising from cryptic splicing, splicing inhibitors may reduce cancer viability through the same mechanism." (PMID 39221819, 2024). "Moreover, the pan-cancer analysis further demonstrated the comprehensive landscapes of HNRNPC in different cancers." (PMID 37469973, 2023). "The purpose of this study is to determine the expression and effect of HNRNPC in pan-cancer and to determine whether HNRNPC can be used as a universal cancer marker." (PMID 35344508, 2022). "Previous works exhibit that hnRNPC is required for the stabilization and translation of target mRNAs, and lncRNA has been reported to be involved in the hnRNPC-mediated mRNA stabilization by interacting with hnRNPC, thus promoting cancer metastasis." (PMID 36471363, 2022). "Besides, HNRNPC regulates cancer-specific alternative cleavage and polyadenylation profiles in colon cancer." (PMID 35502201, 2022). "Both HNRNPA2B1 and HNRNPC might be cancer-promoting factors and potential prognostic biomarkers for LUAD." (PMID 36061307, 2022). "To clarify whether HNRNPC affects cancer through protein phosphorylation, we analyzed the existing protein phosphorylation database." (PMID 35344508, 2022). "Heterogeneous nuclear ribonucleoprotein C (HNRNPC), a nuclear RNA-binding protein involved in pre-RNA processing, has been shown to play an important role in alternative splicing, cell cycle, and the invasion of cancer cells." (PMID 36468034, 2022). "To further explore whether the expression of HNRNPC will affect the survival of cancer patients, we analyzed the prognosis of OS and DFS in patients with high and low HNRNPC expression group." (PMID 35344508, 2022). "A statistically significant negative relationship between HNRNPC expression and the estimated infiltration value of cancer-associated fibroblasts was identified in the TCGA tumors LUSC, TGCT, and THYM." (PMID 35344508, 2022). "With all these correlations between hnRNPA2B1 and cancer, this gene may have a high predictive value, as well as another heterogeneous nuclear ribonucleoprotein, hnRNPC." (PMID 36051357, 2022). "In summary, S220 may be a key location of phosphorylation for HNRNPC proteins, and it may play a role in malignancy and cancer progression." (PMID 35344508, 2022). "Notably, pan-cancer analysis showed that HNRNPC was overexpressed in tumoral tissues compared to normal tissues in most common cancers and was also strongly correlated with poor clinical and pathological features." (PMID 35502201, 2022). "In addition, m6A “readers” such as YTHDF1 and HNRNPC also served as promising biomarkers in cancer stemness aspects." (PMID 34345203, 2021). "In many cancers, splicing is dysregulated; therefore, hnRNPC may be overexpressed to compensate and prevent the access of dsRNA to the cytosol." (PMID 34297039, 2021). "Increased hnRNPC has been shown to contribute to cancer stemness and invasive potential in cancers." (PMID 33329703, 2020). "Until now, HNRNPC has been reported to have various functions in several kinds of cancer." (PMID 33134160, 2020).
cancer (continued). "hnRNPC thus represents a potential APA regulator that may be involved in shaping APA profiles during cancer progression." (PMID 31147722, 2019). "Among them, HNRNPC has been experimentally validated as a regulator of dsRNA-induced interferon signaling and immune activation, suggesting it may promote immune suppression and cancer progression via alternative splicing and RNA processing." (PMID 40565233, 2025). "Therefore, we speculate that PTGES3 and HNRNPC could synergistically promote cancer occurrence and development, which needs to be explored further." (PMID 37416927, 2023). "However, the differential expression of HNRNPC has an uncertain effect on the prognosis of many malignancies, and there is no universally accepted criterion for determining the significance of HNRNPC in distinct cancers." (PMID 35344508, 2022). "However, the essential mechanism of HNRNPC function in the cancer progression and poor prognosis for patients remains largely unknown." (PMID 35963855, 2022). "The S220 locus may operate as a phosphorylation site for HNRNPC activation in cancers." (PMID 35344508, 2022). "However, whether HNRNPC is a critical novel regulator of cancer-specific APA for ANLN-210 in HNSCC remains to be explored." (PMID 34344861, 2021). "However, the exact molecular function of hnRNPC needs to be explored in cancer stemness." (PMID 33329703, 2020). "As far as P38 pathway activation in cancer is concerned, in our study, RALYL, HNRNPC, and p38 were investigated, and the results indicated that HNRNPC and p38 are associated with the role of RALYL in CRC." (PMID 40052233, 2025). "Our investigation demonstrated a predominantly positive correlation between HNRNPC expression and both TMB and MSI across different cancer types." (PMID 39735682, 2025). "Therefore, RALYL may bind to HNRNPC to affect its structure to play a role in cancer inhibition." (PMID 40052233, 2025). "Heterogeneous nuclear ribonucleoprotein C (HNRNPC) has been reported as an m6A reader and functions as an RNA-binding protein to recognize m6A modified RNA in cancer metastasis." (PMID 38184608, 2024). "Our Mass Spectrometry analyses revealed the interaction between HNRNPC and Vimentin, an important cytoskeleton protein involved in epithelial-to-mesenchymal transition (EMT) and cancer metastasis." (PMID 38184608, 2024). "To reveal the potential role of m6A regulator HNRNPC, we further analyzed HNRNPC expression, prognosis, TMB, immune checkpoints, and immune infiltration cells in pan-cancer." (PMID 37469973, 2023). "We believe that the cancer-promoting role of ECE2 gene is related to the modification of m6A, which may affect the methylation level of LUAD, especially HNRNPC, through its association with HNRNPC, IGF2BP1, IGF2BP3 or RBM15, and ultimately affect the progression of LUAD." (PMID 36299451, 2022). "Although complex links between heterogeneous nuclear ribonucleoprotein C (HNRNPC) and numerous types of cancer have been shown in both cell and animal models, a comprehensive pan-cancer investigation on the features and activities of HNRNPC is still lacking." (PMID 35344508, 2022). "Heterogeneous nuclear ribonucleoprotein C (HNRNPC) is an RNA-binding protein "reader" of N6-methyladenosine (m6A) methylation, and is related to the progression of various cancers; however, its role in LUAD is unclear." (PMID 33569346, 2021). "The role of RBPs in promoting cancer has been confirmed, and DROSHA, EXOSC8, HNRNPC, MRPS31, RPLP2, and SNRPB have also been reported to be related to the occurrence and development of a variety of tumors." (PMID 33981333, 2021). "hnRNPC is responsible for the regulation of UTR-APA of a group of genes including MTHFD1L, which is closely related to cancer progression." (PMID 33526057, 2021). "Silencing of HNRNPC reduced miR-21 expression and suppressed the AKT-p70S6K pathway and inhibited cancer invasion." (PMID 34345203, 2021).
cancer (continued). "To further explore the role of KHSRP and HNRNPC in predicting cancer prognosis, we analyzed the KHSRP and HNRNPC mRNA expression and the corresponding clinical data from the publicly available GEO database (GSE30219, n = 293; GSE102287, n = 34)." (PMID 31775888, 2019). "HNRNPC, a member of the heterogeneous nuclear ribonucleoprotein (HNRNP) family, plays a crucial role in cellular nucleic acid metabolism and is significantly involved in cancer development." (PMID 40597017, 2025). "In addition, m6A‐recruited the binding proteins, YTHDC1, YTHDC2, YTHDF3, and FMR1 were inversely correlated, while HNRNPC, HNRNPA2B1, YTHDF1, and RBMX positively correlated TSs in most cancer types." (PMID 36239411, 2023). "Additionally, RNA modification genes, such as RBMX, HNRNPC, ALKBH5, and WTAP, play a crucial role in cancer biology." (PMID 38055673, 2023). "In HCC cells, heterogeneous nuclear ribonucleoprotein C inhibited the epithelial-mesenchymal transition through the Ras/MAPK signaling pathway, and arrested the cells in the G0/G1 phase, thereby inhibiting the cancer cell metastasis and proliferation." (PMID 36829196, 2023). "HNRNPC is up-regulated in HCC and has cancer-promoting effects." (PMID 36263426, 2022). "Previous studies showed that hnRNPC could regulate cancer-specific alternative cleavage, which suggested that LINC00924 might regulate premRNA splicing via hnRNPC." (PMID 36418856, 2022). "HNRNPA2B1, HNRNPC, LRPPRC, ALKBH5 showed high expression in almost all cancers." (PMID 35265626, 2022). "In brief, hnRNPAB1 and hnRNPC are highly expressed in several cancers and have negative effects on OS, which is consistent with our result." (PMID 36051357, 2022). "Notably, HNRNPA2B1 and HNRNPC showed extensive expression pattern in all cell types, but the expression of these m6A regulators was higher in M1 macrophages, GBM cancer cells, and T/NK cells." (PMID 35558067, 2022). "According to the recent studies, there were 13 m6A regulator genes confirmed to affect cancer progression, including the “writer” (KIAA1429, METTL3, METTL14, RBM15, WTAP, and ZC3H13), the “readers” (HNRNPC, YTHDC1, YTHDC2, YTHDF1, and YTHDF2), and the “erasers” (ALKBH5 and FTO)." (PMID 34179079, 2021). "Notably, a predominantly negative correlation was noted among HNRNPC levels and immune infiltration levels, particularly notable in certain cancers like WT, TGCT, and GBM." (PMID 39735682, 2025). "The positive pan-cancer correlations with m1A RNA methylation regulatory proteins YTHDF2 and ALKBH1, m5C methylation regulatory proteins DNMT1, DNMT3B, and ALYREF, and m6C RNA methylation regulatory proteins HNRNPC, HNRNPA2B1, and ELAVL1 were particularly significant." (PMID 36090896, 2022). "Compared with the control group, expression levels of HNRNPC, YTHDF1, KIAA1429, RBM15, YTHDF2, and METTL3 in cancer group were significantly up-regulated (P < 0.05), while expression levels of FTO, ZC3H13, METTL14, YTHDC1, and WTAP in cancer group were significantly down-regulated (P < 0.05)." (PMID 33193582, 2020).
infection (4 papers, 2018 to 2025). The state of being infected such as from the introduction of a foreign agent such as serum, vaccine, antigenic substance or organism. "Emerging evidence indicates that hnRNPC participates in the regulation of infection of several viruses, including influenza, poliovirus, dengue virus, Ebola virus, Middle East respiratory syndrome coronavirus (MERS-CoV) and SARS-CoV-2." (PMID 39994817, 2025). "Previous studies have reported that hnRNPC protein was involved in the infection of hepatitis delta virus (HDV), dengue virus (DENV), Japanese encephalitis virus (JEV), and hnRNPU protein functioned as a nuclear sensor for viral RNA." (PMID 32582087, 2020). "The expression of hnRNPC significantly increased at 6, 12 and 24 h after SVCV infection and returned to basal level at 48 h." (PMID 39994817, 2025).
adenocarcinoma (3 papers, 2019 to 2024). A common cancer characterized by the presence of malignant glandular cells. "Interestingly, the IGF2BP1, IGF2BP2, and HNRNPC genes displayed strong prognostic performance in adenocarcinoma, as validated in two independent cohorts of patients." (PMID 38539567, 2024). "We show that a reduction of hnRNPC levels in metastatic-derived SW620 cells reverts the APA profile of several genes including MTHFD1L to those characteristic for normal- and adenocarcinoma-derived cells." (PMID 31147722, 2019).
neurodevelopmental disorder (1 paper, 2025). A behavioral and cognitive disorder with onset during the developmental period that involves impaired or aberrant development of intellectual, motor, or social functions. "Background/Objectives: Heterozygous variants in the heterogeneous nuclear ribonucleoprotein C gene (HNRNPC) have recently been reported to cause intellectual developmental disorder-74 (MRD74), a neurodevelopmental disorder with no recurrent diagnostic handles." (PMID 40004505, 2025).
HNRNPC also shares sentences with these, for which no sentence is quoted: frontotemporal dementia (3 papers); Skin Cutaneous Melanoma (3); cholangiocarcinoma (2); neurodegenerative disease (2); thymoma (2); abdominal aortic aneurysm (1); acute myeloid leukaemia (1); acute promyelocytic leukemia (1); adenomyosis (1); asthma (1); bladder tumors (1); cardiovascular disease (1); diabetes mellitus (1); diffuse large B-cell lymphoma (1); End-Stage Renal Failure (1); esophageal adenocarcinoma (1); esophageal tumors (1); glial cell tumors (1); head and neck cancer (1); heart disease (1); Hepatic steatosis (1); influenza (1); invasive ductal carcinoma (1); kidney cancer (1); meningioma (1); mesothelioma (1); metabolic disorders (1); Other (1); ovarian insufficiency (1); Pan (1).
A further 6 diseases each share a sentence with HNRNPC in 1 paper.